PHF19 (PHD finger protein 19)
Diseases named in the same sentence as PHF19 in open-access papers (continued):
Sharing a sentence is not in itself a finding about the gene and the disease.
ovarian carcinoma (continued). "Moreover, the findings that CFG exerts an anti-tumor effect and PHF19 functions as an oncogenic role in ovarian cancer promote us to examine the relationship between CFG and PHF19 in ovarian cancer." (PMID 32180719, 2020). "Importantly, rescue the expression of PHF19 reverted CFG-induced suppression in ovarian cancer cell growth, EMT and stemness, while PHF19 knockdown accelerated CFG’s anti-tumor effect." (PMID 32180719, 2020). "Moreover, PHF19 is found to be a direct target of miR-211 in ovarian cancer." (PMID 32180719, 2020). "Herein, we sought to determine whether PHF19 plays a role in ovarian cancer stemness." (PMID 32180719, 2020). "As expected, PHF19 knockdown could accelerate CFG-induced cell apoptosis in ovarian cancer." (PMID 32180719, 2020). "In the present study, we systematically elucidated the role of PHF19 in ovarian cancer proliferation, apoptosis, invasion, migration and stemness, which may help us to find a potential molecular target for the prevention and treatment of ovarian cancer." (PMID 32180719, 2020). "By sponging miR-211, MALAT1 up-regulates PHF19 expression and induces RBFOX2 expression and alternative processing of the tumor suppressor gene KIF1B, leading to ovarian cancer cell proliferation, invasion, increased anoikis, and anchorage-independent growth." (PMID 32174966, 2020). "In ovarian cancer cells, MALAT1 sponges miR-211, thus up-regulating PHF19 expression and facilitating ovarian cancer progression." (PMID 32174966, 2020). "Then, the viability of HEY-T30 and SKOV3 ovarian cancer cells with/without PHF19 overexpression or knockdown was evaluated in the presence of different concentrations of CFG (HEY-T30: 0, 0.75, 1.5, 3, 6, 9, 12, 18, and 24 mg/ml; SKOV3: 0, 0.75, 1.5, 3, 6, 9, 12, 15, and 18 mg/ml) for 24 h." (PMID 32180719, 2020). "In our previous study, we have also preliminarily proved that PHF19 may act as an oncogene in ovarian cancer SKOV3 cells by using RNAi technology, however, its exact role in the biological behaviors of ovarian cancer, especially its role in drug-resistance, needs to be further investigated." (PMID 32180719, 2020). "We found that overexpression or knockdown of PHF19 could not influence the chemoresistance of HEY-T30 and SKOV3 to cisplatin, suggesting that the drug-resistance of ovarian cancer cells induced by PHF19 may be specific for CFG." (PMID 32180719, 2020). "Here, we also determined the expression of miR-211 in ovarian cancer cells with 0, 3 and 12 mg/ml of CFG treatment for 24 h and found that CFG could not influence the expression of miR-211, suggesting that CFG-induced PHF19 downregulation is not mediated by miR-211." (PMID 32180719, 2020).
prostate carcinoma (6 papers, 2017 to 2023). A carcinoma that arises from epithelial cells of the prostate gland. "Finally, with the loss of PHF19, prostate cancer cells switch to a less proliferative but more aggressive phenotype." (PMID 32155117, 2020). "In the context of prostate cancer, a study demonstrated that the depletion of the full-length PHF19 unexpectedly leads to increased chromatin binding of PRC2." (PMID 37107696, 2023). "Another study suggests that the short isoform of PHF19 is also important for the proliferation and migration of prostate cancer cells, suggesting a sophisticated role of PHF19 in this cancer type." (PMID 37107696, 2023). "Our findings reveal a role for PHF19 in controlling the balance between cell proliferation and invasiveness in prostate cancer." (PMID 32155117, 2020). "We further report for the first time the genome-wide PHF19 target genes in prostate cancer and show its co-localization with PRC2 and H3K27me3." (PMID 32155117, 2020). "In this study, we report a novel role for PHF19 in controlling the balance between growth and invasiveness in prostate cancer." (PMID 32155117, 2020). "In order to explore the role of PHF19L on chromatin in prostate cancer, we carried out chromatin immunoprecipitation using an anti-PHF19 antibody followed by high-throughput sequencing (ChIP-seq) in DU145 cells." (PMID 32155117, 2020). "Finally, in prostate cancer, we employed a similar strategy to evaluate the effects of the KD of PHF19, a PRC2 subunit, using SeqCode." (PMID 34599234, 2021). "To investigate whether PHF19 also affects PRC2 binding in prostate cancer, we analyzed the genome-wide occupancy of PRC2 subunits and the H3K27me3 mark, in control (shCTR) and PHF19L-depleted (shPHF19L#4) DU145 cells." (PMID 32155117, 2020). "To investigate the role of PHF19 in prostate cancer, we first evaluated its expression in two common human prostate cancer cell models, the poorly-differentiated metastatic PC3 and DU145 cell lines, as well as in a normal counterpart, the prostate epithelial cell line RWPE1." (PMID 32155117, 2020). "Our data show that only the long isoform of PHF19 interacts with PRC2 in prostate cancer cells." (PMID 32155117, 2020). "Here, we investigate the role of PHF19 in prostate cancer cells." (PMID 32155117, 2020). "In a similar way in HSCs and prostate cancer cells, PHF19 KD was associated with increased levels of H3K27me3, and with a repression of a subset PRC2 target genes suggesting that in some context PHF19 may have PRC2 inhibitory functions." (PMID 34857028, 2021). "Whether or how PHF19 modulates the function and targets of the EZH2 in prostate cancer remains to be explored." (PMID 32155117, 2020). "However, to date a global comprehensive analysis aimed at identifying the genetic targets and pathways controlled by PHF19 in cancer has not been reported (except one study in a prostate cancer cell line)." (PMID 34857028, 2021).
gastric cancer (5 papers, 2021 to 2023). A primary or metastatic malignant neoplasm involving the stomach. "Aberrant overexpression of PHF19 has also implicated in gastric cancer, associated with cancer cell differentiation and poor prognosis for patients." (PMID 35069553, 2021). "Further studies suggest a role of PHF19 in other cancer types, such as ovarian and gastric cancer, for which PHF19 has mostly been described to function as an oncogene." (PMID 37107696, 2023). "In our research, CCK-8 and clone formation experiments confirmed that PHF19 could promote the malignant proliferation of CRC cells through its high expression, which is consistent with the results of previous studies in gastric cancer." (PMID 34141488, 2021).
liver cancer (5 papers, 2020 to 2022). An epithelial or non-epithelial malignant neoplasm that arises from the liver. "Studies have shown that miR-195–5p inhibits the proliferation, migration and invasion of liver cancer cells by regulating PHF19." (PMID 35309118, 2022). "PHF19 interacted with the components of β-catenin inhibitor in the intercellular substance, inhibiting the decomposition of β-catenin, and promoted the signal transduction of β-catenin/T cells, thereby increasing the level of downstream IL-6 and promoting the movement of liver cancer cells." (PMID 34141488, 2021). "While a pro-tumorigenic role of STK39 and PHF19 has already been proposed in human HCC, the potential function of KLC2 in liver cancer has remained elusive and was thus investigated in more detail." (PMID 35563834, 2022). "Using a LINC00152 knockout approach KLC2, PHF19, and STK39 were validated as being regulated by the LINC00152 ceRNA network in liver cancer." (PMID 35563834, 2022).
cardiac hypertrophy (4 papers, 2021 to 2025). "Our findings demonstrated that PHF19 promoted cardiomyocyte hypertrophy in vitro and cardiac hypertrophy in vivo." (PMID 33611744, 2021). "During cardiac hypertrophy, Ang II treatment reduced the enrichment of H3K36me3 at Sirt2 promoter in heart tissues, which was blocked by Phf19 knockdown." (PMID 33611744, 2021). "In the present study, we identified that PHF19 promoted cardiac hypertrophy via downregulating SIRT2." (PMID 33611744, 2021). "Of importance, we demonstrated that PHF19 promoted stress-induced cardiac hypertrophy and facilitated the decline in fraction shortening and ejection fraction." (PMID 33611744, 2021). "We also observed that PHF19 knockdown with AAV9-mediated shRNA repressed pathological cardiac hypertrophy in vivo." (PMID 33611744, 2021). "In the present study, we provided evidence that PHF19 promotes cardiac hypertrophy via epigenetically repression SIRT2 expression." (PMID 33611744, 2021). "Here in this work, we observed that PHF19 promoted cardiac hypertrophy via epigenetically targeting SIRT2." (PMID 33611744, 2021). "In conclusion, we identified PHF19 as a pro-hypertrophy factor in pathological cardiac hypertrophy." (PMID 33611744, 2021). "Therefore, our findings demonstrated that PHF19 promoted the development of cardiac hypertrophy via epigenetically regulating SIRT2." (PMID 33611744, 2021). "Overall, PHF19 acts as a pro-hypertrophic factor and may serve as a target for the treatment of cardiac hypertrophy." (PMID 33611744, 2021). "Next, we tested the functional importance of PHF19 in cardiac hypertrophy in vivo." (PMID 33611744, 2021). "Therefore, PHF19 may serve as a target for the treatment of cardiac hypertrophy." (PMID 33611744, 2021). "However, the roles of PHF19 in cardiac hypertrophy remain unknown." (PMID 33611744, 2021). "PHF19 epigenetically regulated SIRT2, which aided in the development of heart hypertrophy." (PMID 41567643, 2025).
leukemia (3 papers, 2019 to 2021). A malignant (clonal) hematologic disorder, involving hematopoietic stem cells and characterized by the presence of primitive or atypical myeloid or lymphoid cells in the bone marrow and the blood. "Three human myeloid-related leukemia cell lines (one of chronic myeloid leukemia origin: K562; two from acute promyelocytic leukemia: HL60 and NB4) were depleted for the long isoform of PHF19 using two different short hairpin RNAs (shRNA) (inner panels)." (PMID 33996816, 2021). "MiR-124a inhibited PHF19 over-expression and hindered cell growth in human glioma, while miR-19a and miR-19b down-regulated the expression of BARD1 in leukemia." (PMID 30634442, 2019).
rheumatoid arthritis (3 papers, 2021 to 2024). A chronic, systemic autoimmune disorder characterized by inflammation in the synovial membranes and articular surfaces. "The critical roles of PHF19 were observed in stem cell maintenance and differentiation, cancer biology, reprogramming of T cells, and rheumatoid arthritis." (PMID 33611744, 2021). "Furthermore, genetic studies of rheumatoid arthritis heritability identified single nucleotide polymorphisms (SNPs) in the Chr 9q33.2 region involving PHF19, TRAF1 and C5 as genetic risk factors for rheumatoid arthritis." (PMID 34857028, 2021). "For instance, the perturbation of an enhancer element upstream of PHF19 that overlaps SNPs in the 95% credible set for a rheumatoid arthritis GWAS signal resulted in immune-related DEGs not reported in K562 cells, including TRAF1." (PMID 38308274, 2024).
breast carcinoma (2 papers, 2012 to 2021). "The rationale for picking Phf19 and Foxl1 was that their expression was frequently deregulated in primary human breast carcinomas." (PMID 23131872, 2012).
chronic myeloid leukemia (2 papers, 2021). "We demonstrated that PHF19 depletion decreases cell proliferation and promotes chronic myeloid leukemia (CML) differentiation." (PMID 33996816, 2021).
colon cancer (2 papers, 2025). "Among the genes implicated in colon cancer, a comprehensive analysis of available transcriptomic data indicated the PHF19 gene as being a potential candidate." (PMID 40563408, 2025). "The PHF19 gene promoter found to be upregulated in colon cancer tissue gives rise to the transcript PHF19-207 (Transcript ID: ENST00000456291)." (PMID 40563408, 2025). "The UCSC Xena Browser web server indicated down-regulation of PHF19-207 in GTEx normal colon tissue and its upregulation in TCGA colon cancer tissue samples, with a p-value of 1.442 × 10−9." (PMID 40723829, 2025). "The objective of this study was to investigate the function of PHF19-207 using in silico tools and publicly available data, as well as to assess its expression in colon cancer." (PMID 40723829, 2025). "In silico data also point to the upregulation of PHF19-207 in colon cancer tissue samples in comparison to normal colon mucosa." (PMID 40723829, 2025). "The results of this study provide us with detailed data on PHF19 expression through the development of colon cancer and suggest the potential use of PHF19-207 as a biomarker of early colon cancer." (PMID 40723829, 2025). "This study has demonstrated the potential of the transcript PHF19-207 for early colon cancer detection and proposes a dual role of PHF19-207 that should be further investigated." (PMID 40723829, 2025). "This study was conducted using cell lines, high-throughput sequencing and computational tools to evaluate the potential of the transcript PHF19-207 as a biomarker for early colon cancer and to explore its possible role in tumor promotion." (PMID 40723829, 2025). "The potential of the PHF19-207 transcript as a biomarker for colon cancer screening deserves further investigation, especially with regard to its applicability in non-invasive testing methods." (PMID 40563408, 2025). "A recent comprehensive pan-cancer study indicated the high translational potential of the transcript PHF19-207 as a biomarker for colon cancer." (PMID 40563408, 2025). "One of these promoters upregulated in colon cancer leads to the expression of the PHF19-207 transcript, suggesting its potential role in tumor promotion." (PMID 40723829, 2025). "The analysis revealed a significantly higher expression of the PHF19-207 transcript in primary tumor tissues compared to solid normal tissues from colon cancer patients (TCGA: primary tumor vs. solid tissue normal, p = 3.511 × 10−12)." (PMID 40563408, 2025). "Importantly, future research should also investigate whether the PHF19-207 transcript expression is associated with tumor progression, which could provide deeper insight into its biological significance and reveal its potential as a prognostic biomarker or therapeutic target in colon cancer." (PMID 40563408, 2025). "Given its differential expression in malignant versus normal tissue, the PHF19-207 transcript may serve as a valuable screening biomarker for early-stage colon cancer." (PMID 40563408, 2025). "Furthermore, increased expression of the PHF19-207 transcript was observed in malignant colon cancer cell lines compared to a non-malignant control, further supporting its potential role in colon cancer pathophysiology." (PMID 40563408, 2025). "Based on the findings of this study, the PHF19-207 transcript shows strong potential as a diagnostic biomarker for colon cancer, particularly for distinguishing malignant from non-malignant tissue." (PMID 40563408, 2025). "Increased secretion of PHF19-207 via exosomes in colon cancer could elucidate its mechanism of action in cancer development and should be further explored." (PMID 40723829, 2025). "Notably, the increase in PHF19-207 expression was more pronounced in cell lines representing advanced stages of colon cancer." (PMID 40723829, 2025).
colon cancer (continued). "Surgical samples of tumor and adjacent non-tumor tissue from non-metastatic, treatment-naive colon cancer patients were analyzed to evaluate the diagnostic potential of the PHF19-207 transcript and its association with tumor characteristics." (PMID 40563408, 2025). "Moreover, given its higher expression in colon cancer tissues and the stability of cell-free RNA in circulation, the PHF19-207 transcript could potentially support the early detection of colon cancer, which is critical for more effective treatments." (PMID 40563408, 2025). "Preliminary evidence suggests that the PHF19-207 transcript is upregulated in colon cancer tissue, raising the possibility that this non-coding transcript may contribute to the molecular pathogenesis of colon cancer by modulating the key regulatory networks involved in tumor development." (PMID 40563408, 2025). "The hypothesis on its involvement in the early stages of colon cancer was derived from a previous comprehensive study that had screened for the deregulation in the genes’ promoter activity between tumor and non-tumor tissue and found deregulation in the activity of the PHF19 gene promoters." (PMID 40723829, 2025). "Additionally, a lower expression of the PHF19-207 transcript in samples of healthy mucosa was observed in comparison to non-tumor tissue samples from colon cancer patients, highlighting the complexity of its potential application in early-stage detection." (PMID 40563408, 2025).
Ewing sarcoma (2 papers, 2021 to 2023). A small round cell tumor that lacks morphologic, immunohistochemical, and electron microscopic evidence of neuroectodermal differentiation. "An oncogenic role of PHF19 has also been demonstrated in Ewing Sarcomas, where the PHF19 gene is downstream of the EWS/ETS fusion proteins that typically drive the oncogenic program in this cancer type." (PMID 37107696, 2023). "EWS/FLI1 fusion in Ewing sarcoma was shown to regulate PHF19 expression by collaborating with BET proteins and the binding of a distal regulatory element (enhancer) of PHF19." (PMID 34857028, 2021).
adenoma (1 paper, 2025). A neoplasm arising from the epithelium. "This dataset also showed moderate upregulation of PHF19-201 and PHF19-202 in adenoma and tumor tissue in comparison to mucosa." (PMID 40723829, 2025). "However, an analysis of the expression of this transcript in mucosa, adenoma, and tumor colon tissues (dataset GSE164541) showed a prominent increase in expression of PHF19-207." (PMID 40723829, 2025). "However, no trend was observed in the expression of PHF19-210 among healthy mucosa, adenoma and tumor tissues." (PMID 40723829, 2025).
adrenocortical carcinoma (1 paper, 2021). "Besides, we further evaluated the correlation of PHF19 expression with cancer pathological stages, including ACC (adrenocortical carcinoma), BLCA (bladder urothelial carcinoma), KICH, KIRC, LIHC, LUSC, and THCA." (PMID 35069553, 2021).
astrocytoma (1 paper, 2013). "Among them, the expressions of EZH2 and PHF19 correlated positively with the astrocytoma grades, whereas the expressions of CBX7, CBX6 and EZH1 correlated negatively with astrocytoma grades." (PMID 24260522, 2013). "CBX6, CBX7 and EZH1 shared a similar pattern and correlated negatively with increasing astrocytoma grade, whereas the opposite occurred with EZH2 and PHF19." (PMID 24260522, 2013). "Interestingly, changes in EZH2, PHF19, CBX7, CBX6 and EZH1 occurred progressively as astrocytoma grade increased." (PMID 24260522, 2013).
bladder cancer (1 paper, 2021). "The results revealed that high PHF19 expression predicted worse OS in BC (bladder carcinoma), KIRC, KIRP, LIHC, LUAD, LUSC, and UCEC, nevertheless, patients with higher PHF19 expression showed remarkably improved OS in HNSC, SARC, THCA, and THYM (all log-rank P values < 0.05)." (PMID 35069553, 2021).
breast tumor (1 paper, 2022). "The negative correlation between CTR9 and PRC2.1 facultative subunits (PHF1/MTF2/PHF19 and EPOP) at the mRNA level was also observed in 817 ER-positive primary breast tumor samples in TCGA." (PMID 35137163, 2022).